CCR2 (C-C motif chemokine receptor 2)
Diseases named in the same sentence as CCR2 in open-access papers (continued):
Sharing a sentence is not in itself a finding about the gene and the disease.
infection (continued). "In aggregate, these findings indicate that CCR2 depleter mice produce wild-type levels of CXCL1 and CXCL2 during respiratory fungal infection and display preserved neutrophil recruitment to the site of infection, though these processes per se are insufficient to prevent the development of IA." (PMID 24586155, 2014). "The dual role of macrophages being crucial to limit and contain bacterial in the onset of infection and serving as host cell in later stages may also explain the higher bacterial load obtained in CLN of CCR2 knock out mice that have decreased numbers of peripheral monocytes." (PMID 25919005, 2014). "Based on our findings, the proportion of CCR2+ inflammatory monocytes in the blood and concentration of CCR2 ligands in the serum have potential as translational biomarkers to predict IAV virulence and pathogenesis in an emerging pandemic infection and sporadic infections of avian IAVs." (PMID 25407417, 2014). "Interestingly, while relative proportions of CCR2−/− NK cells were low in the BAL, the ratios of CCR2−/− : wt NK cell in the lungs did not change over the course of infection." (PMID 23272202, 2012). "Neighboring CCR2 and CCR5 gene variants (haplotypes and diplotypes) have well-known relationships to HIV-1 transmission (initiation of infection), but their role in established infection is not persuasive." (PMID 23202454, 2012). "In WT but not in CCR2 KO mice this treatment mimicked the phenotype observed in IL-10 KO mice, killing the mice at 11±1 days post infection with increased liver injury (serum ALT levels: 810±68 versus 223±39 U/ml in anti-IL-10R and control antibody treated WT mice at day 10 post infection)." (PMID 20714353, 2010). "Therefore, future analyses of CCR2-depleted BALB/c mice might interrogate distinct mechanisms of MuHV-4-induced suppression of AMs, which could also highlight beneficial or detrimental effects in front of viral heterologous infections." (PMID 35062301, 2022). "Thus, the relative importance of CCR2 in primary intracellular infections remains an open question, and its role in secondary challenge with an intracellular pathogen, following survival of a first infection or following vaccination, has not been evaluated." (PMID 33760886, 2021). "Surprisingly, the chemokines responsible for susceptibility could not be identified either individually or in combination: mice deficient in MCP-1/CCL2, MCP-3/CCL7 KO mice, or MCP-5/CCL12, the major known murine ligands for CCR2, were not unusually susceptible following ID LVS infection." (PMID 33760886, 2021). "However, a rechallenge of previously infected Ccr2-/- mice revealed increased bacterial killing (as indicated by a reduction in S. aureus CFU), decreased infiltrating PML, and less skin IL-1β concentrations as compared to naïve counterparts 5 days after (re-)infection." (PMID 32639232, 2020). "Importantly, treatment significantly reduced both the frequency and absolute number of Ly6C+CCR2+CX3CR1+/- inflammatory or Ly6C+CCR2-CX3CR1+ inflammatory monocyte derived cells in LmLm mice, demonstrating that IFN-γ drives a proportion of monocyte recruitment during secondary infection." (PMID 28666021, 2017). "Administration of IL-12 during infection restored the bacterial burdens in the BALF and lungs of monocyte-depleted CCR2-DTR mice to the levels of WT mice, independent of IFN-γ." (PMID 39418302, 2024). "Here, we confirmed that spleens of both wild type and CCR2 KO mice contained MCP-1/CCL2 and MCP-5/CCL12 within two days of LVS infection; reagents to quantitate MCP3 were not available." (PMID 33760886, 2021). "Nonetheless, at this LVS infection dose, mice lacking circulating MCP-1/CCL2, MCP-3/CCL7, and MCP-5/CCL12 largely survived, while CCR2 KO mice did not." (PMID 33760886, 2021). "In previous studies of Francisella infections, splenic monocyte populations did not expand quickly in CCR2 KO mice given LVS IV, and spleens had higher bacterial burdens within the first day of infection." (PMID 33760886, 2021).
infection (continued). "However, infected Ccr2-/- mice, in which CD11b+Ly6Chigh monocytes recruitment to the infected tongue was strongly impaired, displayed no defect in IL-17A production on day 1 post-infection by any of the three CD90+ cell subsets (TCRβ+, TCRγδ+, ILCs) compared to WT control mice." (PMID 29782555, 2018). "Nematode infection did not affect the expression of adhesion molecule VLA-4 on lymphocytes and of CCR2 on macrophages, and these receptors were highly expressed on leukocytes of all immunized mice." (PMID 28975357, 2018). "Interestingly, CCR2-positive cells that also express the microglia marker Iba1 were detected in brain sections of the olfactory bulb (not shown) and the medulla of WT, CCR2-/-→WT and WT→CCR2-/- mice on days 6 and 8 (not shown) post-infection (p.i.)whereas no signal was detected in CCR2-/- group." (PMID 27930721, 2016). "Emigration of Ly6Chi CCR2+ cells from the bone marrow is directed by MCP-1 and MCP-3, which is mainly produced by non-hematopoietic cells during infection and can be produced by bone marrow mesenchymal stem cells (BMSCs) in response to circulating TLR ligands." (PMID 24945711, 2014). "After infection with P. chabaudi the strongly reduced compartment of BM “CD27+ CMPs” and “GMPs” lacked detectable surface levels of CCR2 suggesting that residual myeloid progenitors were unable to egress from the BM via this chemokine-signaling pathway." (PMID 23762028, 2013). "The CCR2 antagonist, or DMSO control, by itself did not have a significant effect on infection." (PMID 34277460, 2021). "Infection status could also predict CD64 and CCR2 surface levels over time; albeit lack of ability to predict that of CXCR2 receptors." (PMID 33424860, 2020). "We found that the majority of CD11b+ LyChi Ly6G- CD64+ inflammatory monocytes present in the ear of VACV-infected mice at 5 days post-infection were CCR5+, the receptor for CCL4, rather than CCR2+, or positive for the receptors for CXCL13 (CXCR5) or CXCL9 and CXCL10 (CXCR3)." (PMID 31603920, 2019). "In the anti-CCR2 treated group 29% of the mice had no parasites compared to 5% in the rat IgG treated group, a striking effect given the BALB/c mice typically have not cleared the infection until ~day 90 pi." (PMID 29299998, 2018). "Interestingly, both CCR2+ inflammatory monocytes and monocyte-derived dendritic cells show increased transcription of the Il1a gene at 48 h post-A.fumigatus challenge, but whether lung-resident CCR2+ monocytes could contribute to IL-1α production at early times after infection was not explored." (PMID 25629406, 2015). "While absence of CCR2 could only affect recruited CD11b+Ly6C+ monocytic cells, absence of IFN-γ and MyD88 signaling can impair the activation of both recruited and resident liver monocytic cells during infection." (PMID 20714353, 2010). "However, neither CCR2-/- nor CX3CR1-/- mice demonstrated marked systemic spread of virus following dermal VACV infection, indicating that, unlike in the intranasal infection model, locally recruited macrophage populations are unlikely to play a role in restricting VACV to the skin." (PMID 28614386, 2017).
bacterial infection (27 papers, 2010 to 2025). "Recently, it has been shown that topical treatment with the CCR2 antagonist (JNJ17166864) reduced alveolar bone loss from bacterial infection in mice supporting a role for CCR2 in bone loss." (PMID 28424660, 2017). "Research on CCR2 has predominantly focused on monocyte migration, with limited understanding of its role in intracellular bacterial infections." (PMID 39903705, 2025). "Mouse models have demonstrated that CCR2 is required for Ly6C+ monocytes, which are important during bacterial infection." (PMID 37566040, 2023). "On the other hand, the study on the mice model evidenced that expression of CCR2 was a major mediator of macrophage recruitment and transport and host defense against bacterial infection." (PMID 37190028, 2023). "Here, we show that γδT17 cells expand in draining LNs and infiltrate nasal mucosa via CCR2 during bacterial infection." (PMID 28580944, 2017). "During bacterial infection the activation of CCR2 on classical monocytes is required for them to exit the bone marrow, whereas it is dispensable for directed movements in the bloodstream toward the infected tissue." (PMID 26029924, 2015). "Ly6Chi CCR2+ inflammatory monocytes were first identified in L. monocytogenes infection, where they differentiate into TipDCs at the sites of bacterial infection and are essential for early control of bacterial replication." (PMID 24945711, 2014). "A report by Serbina and Pamer suggested that monocyte emigration from bone marrow during bacterial infection requires signals mediated by the chemokine receptor CCR2." (PMID 20419144, 2010). "Whether a bacterial infection superimposed upon a injured brain alters CCL2/CCR2-mediated monocyte activity remains unclear." (PMID 38720343, 2024). "Since CCR2+ inflammatory monocytes mediate host defense against bacterial infection, we investigated whether this cell population was functionally impaired in Clec5a−/− and Clec5a−/−Tlr2−/− mice." (PMID 28824166, 2017). "During L. monocytogenes infection, Ly6Chi CCR2+ cells emigrate from the bone marrow in a CCR2-dependent manor, and traffic to sites of bacterial infection to differentiate into CD11C+ TNF-α and inducible nitric oxide synthase (iNOS) producing DCs (TipDCs) that enhance bacterial clearance." (PMID 24945711, 2014). "CCR2+ cells are known to be broadly important to host defense against bacterial infections." (PMID 23633954, 2013). "Therefore, during bacterial infection of mice, CCR2-expressing CD11b+Ly6Chi cells can acquire DC-like characteristics and have direct antimicrobial activity, but it is unclear if these cells can differentiate into infDC and prime or activate CD8+ T cell responses to microbial antigens." (PMID 26468944, 2015). "CCR2 and CCL2 knockout mice therefore cannot mobilize classical monocytes upon bacterial infection and die because they cannot suppress bacterial growth." (PMID 26029924, 2015). "The researchers found that CCR2+ monocytes produced high levels of CXCL1, which directly recruited CXCR2-expressing neutrophils to the lungs, contributing to the host defense against bacterial infection." (PMID 38596679, 2024). "Our observational studies in humans imply that the numbers of intermediate (CD14++CD16-) monocytes, which we have previously shown express higher levels of CCR2 with age, correlate with increased levels of TNF and contribute to hyper-inflammatory responses to bacterial infection." (PMID 26766566, 2016). "In CCR2 knockout mice, and to a lesser extent CCL2 knockout mice, classical monocytes do not enter the bloodstream efficiently and instead accumulate in the bone marrow after bacterial infection." (PMID 26029924, 2015). "Moreover, CCR2+ TVM cells show superior protection against unrelated bacterial infections compared with CCR2- TVM cells and TN cells, but the mechanism by which CCR2+ TVM cells act directly or helps other types of immune cells remains unclear." (PMID 39193473, 2024).
bacterial infection (continued). "Of importance, BCG‐vaccinated CCR2−/− animals lacking circulating monocytes were not only better protected than their unvaccinated counterparts in terms of bacterial infection in the lung and spleen but were also as well protected as BCG‐vaccinated WT hosts with circulating monocytes." (PMID 37158369, 2023).
cardiovascular diseases (25 papers, 2014 to 2025). "Recently, single-cell RNA sequencing (sc-RNAseq) revealed that both CCR2– and CCR2+ subsets of CRMs are enriched in pathways of wound healing, angiogenesis, and vasculature development in cardiac development and cardiovascular diseases." (PMID 38763956, 2024). "This approach has effectively reduced CCR2+ monocyte levels in circulation and their infiltration into tissues, such as the heart, in cardiovascular diseases." (PMID 39201480, 2024). "Including the Rh blood group antigen genes RHD and RHCE and CCR2 and CCR5 due to the high homology between the sequence, which are associated with immunologic and cardiovascular diseases." (PMID 39872888, 2023). "Our findings invite to revisit the experimentation on therapeutic approaches based on CCR2 antagonists for the prevention of cardiovascular disease." (PMID 35711383, 2022). "All these studies together with our novel findings that CCR2 gene expression in monocytes was up-regulated in severe OSA patients provide new evidence for the close association of OSA and cardiovascular diseases." (PMID 25411969, 2014). "Further, our main results for associations between CCR2 variants and cardiovascular disease endpoints failed to reach the formal threshold of statistical significance for gene-based testing (p < 2.7 × 10−6)." (PMID 40119478, 2025). "Thus, our study provides a comprehensive framework and transcriptional resource for assessing the impact of aging on CCR2– and CCR2+ CRMs, which play critical roles in the pathogenesis of various cardiovascular diseases." (PMID 38763956, 2024). "Restrictions concerning the therapeutic benefits of CCL2/CCR2 antagonists and antibodies in the management of cardiovascular disorders encompass the assessment of off-target consequences, toxicity, and the possibility of compensatory activity by alternative receptors." (PMID 39125901, 2024). "Summary of selected studies investigating the role of CCL2 & CCR2 in cardiovascular diseases." (PMID 36110847, 2022). "Previously case-control studies conducted in Santander, Colombia, have identified SNPs significantly associated with CCC severity in CCR2 and CCR5 loci, which encode two CC chemokine receptors involved in the trafficking of leukocytes and in cardiovascular diseases pathogenesis." (PMID 30650073, 2019). "Among them, CCR2 and its ligands, CCL2 and CCL7 play an important role, so the main objective of this work was to determine whether genetic variants affecting their activity were associated with cardiovascular disease." (PMID 35711383, 2022). "Dual blockade of CCR2 and CCR5 was thought to be a potential therapeutic approach for immunologic and cardiovascular diseases." (PMID 33968046, 2021). "The role of CCR2 in CD4+ T cells in the context of cardiovascular disease has not been elucidated." (PMID 36077273, 2022). "CCR2 represents the receptor for monocyte chemotactic protein 1 (MCP-1), which is one of the main chemotactic factors attracting pro-inflammatory monocytes towards the side of inflammation and plays an important role in the development of cardiovascular diseases." (PMID 34651218, 2021).
inflammation (16 papers, 2014 to 2025). Aberrant reaction of the microcirculation characterized by movement of fluid and leukocytes from the blood into extravascular tissues. "CCR2 is therefore of great importance as both a critical target in modulating the immune system and a potential therapeutic approach for treating inflammation-associated diseases." (PMID 40909274, 2025). "In conclusion, our data indicate that CCR2 and activin A regulate the development of fibrosis during testicular inflammation and underline the crucial pro-fibrotic function of macrophages in inflammation-associated fibrotic remodeling in EAO." (PMID 36434305, 2022). "Our results showed that systolic cardiac dysfunction in Tg MAOA mice was strongly correlated with oxidative stress induced premature senescence of cardiac stromal cells favoring the recruitment of CCR2+ monocytes and the installation of cardiac inflammation." (PMID 33668142, 2021). "Collectively, our findings demonstrate that in immature mice repetitive LPS exposure, through TLR4 signaling increases lung inflammation and impairs lung alveolar growth in a CCR2-dependent manner." (PMID 33117383, 2020). "Studies using our technique to determine VEGF in models of chronic ocular inflammation are warranted to clarify the therapeutic value of CCR2-inhibition in AMD." (PMID 24714223, 2014). "Indeed, in Result 2 of this study, we observed an enhanced recruitment of neutrophils in the lung of ccr2-/- mice, accompanied by more severe lung inflammation and tissue damage." (PMID 39903705, 2025). "In the current study, we found that blocking CCR2 not only abrogated the beneficial effect of PD-L1 immunotherapy on cognitive performance, local brain inflammation, and pathological manifestations, but also prevented the accumulation of Tregs in the diseased brain." (PMID 34172073, 2021). "CCR2 is predominantly expressed on the surface of monocytes and macrophages, and CVC can impede the chemotaxis of these cells to the site of liver inflammation while also inhibiting their production of several inflammatory cytokines that initiate the inflammatory response by obstructing CCR2." (PMID 40362316, 2025).
metabolic disorders (16 papers, 2012 to 2025). "For instance, the involvement of monocytes, and specifically CCR2-dependent recruitment, was shown to promote metabolic disease." (PMID 36994095, 2023).
neurological disease (12 papers, 2012 to 2024). "We found that CCR2-deficient mice exhibited improved 28-day survival and alleviated neurological disease scores despite a brain fungal burden higher than that of the WT mice." (PMID 34311579, 2021). "This is interesting as the CCR-2/MCP-1 signaling pathway is induced in neurological disorders like epilepsia, and associated with neuroinflammation." (PMID 32033172, 2020). "CCR2-dependent entry of IM into the CNS contributes to immunopathology in several neurological diseases (27, –, 29)." (PMID 34311579, 2021). "Future studies will use these methods of CCR2 gene delivery to microglia in vivo for research in animal models of neurologic disease." (PMID 23288990, 2012). "It has earlier been established that chronic activation of PBMCs via CCL2/CCR2 signaling pathway mediates inflammation in many neurological disorders." (PMID 22685564, 2012). "Chemokine receptors such as CCR2 have been proposed to play critical roles in neurological diseases like Alzheimer45,46 and Multiple Sclerosis6, where it was found to be a critical modulator of the aberrant migration of peripheral T cells towards the site of inflammation." (PMID 33479266, 2021). "Furthermore, CCR2 KO BM recipients that received CD11b+Ly-6Chi monocytes sorted from CD11chi DC-depleted mice showed faster development of neurological disorders after JEV infection than did recipients of CD11b+Ly-6Chi monocytes from vehicle-treated mice." (PMID 26626303, 2015). "Because of lack of neurological disease controls having overlapping or distinct clinical symptoms with ALS, the differences observed in CCR2 levels in the study may reflect the molecular change relevant to diseases of CNS in general, as opposed to ALS disease in specific." (PMID 22685564, 2012).
neurodegenerative disease (10 papers, 2012 to 2022). A disorder of the central nervous system characterized by gradual and progressive loss of neural tissue and neurologic function. "In other neurodegenerative diseases, CCR2 deficiency was also reported to accelerate disease." (PMID 34385589, 2021). "Yet, here we show that Ccr2 deletion also leads to increased phosphorylation of tau protein—an event that is commonly associated with loss of physiological function and gain of pathological function by tau in a variety of neurodegenerative diseases." (PMID 26634348, 2015). "In the healthy adult brain and in chronic neurodegenerative disease states, CD45high CNS MPs express low levels of Ly6c and CCR2 supporting their origin from microglia although it is still possible that peripherally derived macrophages downregulate Ly6c and CCR2 after residing in the CNS." (PMID 29552013, 2018).